SLC22A31 (solute carrier family 22 member 31)
Description:
Organic anion transporter that mediates the uptake of ions.
Tractability: Small molecule: it belongs to a druggable protein family. Antibody: UniProt predicts a signal peptide or a membrane-spanning region.
Gene: Protein-coding gene on chromosome 16 (89,195,761 to 89,201,651, reverse strand). Ensembl gene ENSG00000259803.
Subcellular location: Membrane
Gene Ontology:
Molecular function: transmembrane transporter activity
Biological process: transmembrane transport
Cellular component: membrane
Genetic constraint (gnomAD): Loss-of-function variants: 40 observed, 26.32 expected, observed/expected ratio (o/e) 1.52, 90% interval 1.17 to 1.89. The synonymous counts are far from expectation, so gnomAD's model fits this gene poorly and the ratio says little. Missense variants: 553 observed, 459.09 expected, observed/expected ratio (o/e) 1.2, 90% interval 1.12 to 1.29. Synonymous variants: 272 observed, 214.92 expected, observed/expected ratio (o/e) 1.27, 90% interval 1.14 to 1.4.
Homologues: Orthologues: macaque SLC22A31 (90% identical), guinea pig SLC22A31 (54% identical), dog SLC22A31 (51% identical), tropical clawed frog slc22a31 (38% identical), zebrafish slc22a31 (34% identical), Drosophila melanogaster Orct2 (24% identical), Drosophila melanogaster Balat (24% identical), Caenorhabditis elegans oct-2 (24% identical), Drosophila melanogaster Orct (24% identical), Drosophila melanogaster CG42269 (23% identical), Drosophila melanogaster CG14857 (22% identical), Caenorhabditis elegans K05F1.6 (21% identical), and 33 more. Paralogues in human: SLC22A17 (39% identical), SLC22A23 (34% identical), SLC22A12 (28% identical), SLC22A5 (26% identical), SLC22A8 (25% identical), SLC22A6 (25% identical), SLC22A7 (25% identical), SLC22A1 (25% identical), SLC22A13 (24% identical), SLC22A4 (24% identical), SLC22A11 (24% identical), SLC22A2 (24% identical), and 10 more.
Diseases named in the same sentence as SLC22A31 in open-access papers:
SLC22A31 is named in the same sentence as 8 diseases in open-access papers, as found by Europe PMC text mining. Sharing a sentence is not in itself a finding about the gene and the disease. The quoted sentences say what the papers report.
COVID-19 (3 papers, 2024 to 2025). A disease caused by infection with severe acute respiratory syndrome coronavirus 2. "Co-localization analysis identified LZTFL1, MUC4, OAS1, HLA-C, SLC22A31, FDX2, and MAPT as genes involved in COVID-19-mediated causation of MM." (PMID 38400850, 2024). "In addition to these chromosomes, the causal SNPS of COVID-19 hospitalization on MM are also located in many regions of chromosome 19, involving genes such as PSG5, SLC22A31, FDX2, MAPT and others." (PMID 38400850, 2024). "Although the COVID Host Genomics Initiative (throughout a GWAS meta-analysis) revealed some SNP's (in genes SFTPD, MUC5B, SLC22A31, and ACE2) involved in the susceptibility/or protection against severe COVID-19, the complete human genomic landscape of COVID-19 is incomplete." (PMID 38524554, 2024). "Further, based on results from this study and the COVID-19 host genetics initiative and its update, we further highlight several other genes of interest for our COVID-19 severity hypothesis, namely BCL11A, SLC22A31, SLC6A20, SLC2A5 and HBBP1." (PMID 40240424, 2025). "SLC22A31 is a member of the conserved OAT family of solute carriers which also has a closely related member gene SLC22A17 (not reported to be associated with COVID-19 severity so far)." (PMID 40240424, 2025).
colon cancer (2 papers, 2020 to 2022). "SLC22A31 is the most understudied transporter of the SLC22 family but has been associated with right-side colon cancer." (PMID 32150922, 2020). "GGH, CACNG4, MME, SLC30A2, CKMT2, SYN3, and SLC22A31 were identified as differentially expressed both in glycolytic-cholesterogenic subgroups as well as between colon cancers and healthy samples, and were involved in glycolysis‒cholesterol synthesis." (PMID 36569910, 2022).
breast carcinoma (1 paper, 2022). "Solute Carrier Family 22 Member 31 (SLC22A31) was identified as one of the prognostic genes in right-sided colon cancer, which warrants exploration of its significance in other cancer types as well, including the breast cancer." (PMID 36699376, 2022).
tumor (2 papers, 2022 to 2023). "Interestingly, some of the common down-regulated genes, such as EPHA7 and NSUN7, are known for both their tumor suppressing and promoting roles, or are associated with overall survival (OS) (SLC22A31), while others have clear pro-tumorigenic roles (ADGRF1, LOX, LY6G5C, SNAI2, TNFRSF11B, ZNF233)." (PMID 36769365, 2023).
bacterial infection (1 paper, 2024). "Upregulation of GJB2, VNN1, DUSP4, SerpinB7, and IL10, and downregulation of PKMYT1, S100A4, GGTA1P, and SLC22A31 were most strongly associated with bacterial infection." (PMID 39395995, 2024).
SLC22A31 also shares sentences with these, for which no sentence is quoted: cancer (1 paper); head and neck squamous cell carcinoma (1); invasive breast carcinoma (1).